FCRL3 (Fc receptor like 3)
Description:
Promotes TLR9-induced B-cell proliferation, activation and survival but inhibits antibody production and suppresses plasma cell differentiation. Enhances activation of NF-kappa-B and MAPK signaling pathways in TLR9 stimulated B-cells. Has inhibitory potentional on B-cell receptor (BCR)-mediated signaling, possibly through association with SH2 domain-containing phosphatases. Inhibits cell tyrosine phosphorylation, calcium mobilization and activation-induced cell death induced through BCR signaling. Regulatory T-cells expressing FCRL3 exhibit a memory phenotype, are relatively nonresponsive to antigenic stimulation in presence of IL2 and have reduced capacity to suppress the proliferation of effector T-cells. Acts as a human-specific epitope on the cell surface of oocytes (oolemma) and plays a role during sperm-egg adhesion and fusion. Interacts with the IZUMO1-IZUMO1R/JUNO sperm-egg complex and replaces IZUMO1R/JUNO as IZUMO1 receptor during fertilization, thereby permitting species-specific gamete fusion.
Synonyms: FcRH3; CD307c; IFGP3; IRTA3; SPAP2; SPAP2a; SPAP2b; SPAP2c; SPAP2d; SPAP2e; MAIA
Tractability: Antibody: UniProt places it where antibodies can reach, with high confidence; UniProt predicts a signal peptide or a membrane-spanning region; its Gene Ontology location is reachable by antibodies, with medium confidence.
Gene: Protein-coding gene on chromosome 1 (157,674,321 to 157,700,901, reverse strand). Ensembl gene ENSG00000160856.
Subcellular location: Cell membrane; Cell projection, microvillus membrane
Gene Ontology:
Molecular function: kinase binding; phosphatase binding; protein binding; transmembrane signaling receptor activity
Biological process: negative regulation of B cell receptor signaling pathway; negative regulation of immunoglobulin production; positive regulation of B cell proliferation; positive regulation of MAPK cascade; regulation of B cell activation; regulation of B cell differentiation; regulation of calcium ion import; regulation of toll-like receptor 9 signaling pathway; cell surface receptor signaling pathway; immune response
Cellular component: cell surface; plasma membrane; external side of plasma membrane; microvillus membrane
Genetic constraint (gnomAD): Loss-of-function variants: 84 observed, 75.31 expected, observed/expected ratio (o/e) 1.12, 90% interval 0.93 to 1.34. The upper end of that interval is the gene's LOEUF score, 1.34, which puts it in group 5 of 6, group 1 being the genes least tolerant of losing a copy. Missense variants: 939 observed, 902.15 expected, observed/expected ratio (o/e) 1.04, 90% interval 0.99 to 1.1. Synonymous variants: 371 observed, 359.51 expected, observed/expected ratio (o/e) 1.03, 90% interval 0.95 to 1.12.
Homologues: Orthologues: chimpanzee FCRL3 (97% identical), macaque FCRL3 (87% identical), rabbit FCRL3 (64% identical), pig FCRL3 (60% identical). Paralogues in human: FCRL5 (48% identical), FCRL2 (38% identical), FCRL4 (31% identical), FCRL1 (31% identical), FCRL6 (20% identical), FCRLB (16% identical), PECAM1 (16% identical), FCGR1A (16% identical), FCRLA (13% identical), FCGR2B (11% identical), FCGR2C (10% identical), FCER1A (10% identical), and 5 more.
Diseases named in the same sentence as FCRL3 in open-access papers:
FCRL3 is named in the same sentence as 62 diseases in open-access papers, as found by Europe PMC text mining. Sharing a sentence is not in itself a finding about the gene and the disease. The quoted sentences say what the papers report.
rheumatoid arthritis (25 papers, 2006 to 2026). A chronic, systemic autoimmune disorder characterized by inflammation in the synovial membranes and articular surfaces. "Several investigations have implicated FCRL3 and its functional promoter polymorphism -169 T/C in the pathogenesis of various autoimmune disorders, including rheumatoid arthritis, systemic lupus erythematosus, and autoimmune thyroid diseases." (PMID 39076991, 2024). "High FCRL3 expression has been found in B-lymphocytes and augmented autoantibody production in individuals with the rheumatoid arthritis-susceptible genotype." (PMID 33889124, 2021). "Association of FCRL3, with autoimmune diseases such as rheumatoid arthritis (RA), multiple sclerosis, and Graves’ disease (GD), has been reported recently." (PMID 34466580, 2020). "FCRL3 has been associated with the production of cyclic citrullinated peptide autoantibodies in rheumatoid arthritis (RA) and antibodies to thyroid peroxidase in patients suffering from Graves’ disease." (PMID 28458671, 2017). "When the susceptibility effect of FCRL3 was stratified by NF-κβ1 genotypes, association of FCRL3 polymorphisms with rheumatoid arthritis was observed in patients heterozygous for the NF-κβ1 promoter in a Spanish population." (PMID 27863461, 2016). "SNP rs7528684 in the promoter region of FCRL3 was also previously reported as positively associated with rheumatoid arthritis, systemic lupus erythematosus and GD." (PMID 27863461, 2016). "Further correlation of B cell abnormalities with FCRL3 expression is afforded by significant positive correlation of rheumatoid factor autoantibody titre in individuals with rheumatoid arthritis with the number of susceptible −169 C alleles." (PMID 27863461, 2016). "Apart from rheumatoid arthritis, Graves’ disease and Behcet's disease were also observed to be significantly associated with this polymorphism in the FCRL3 gene." (PMID 26402798, 2015). "The FCRL3 −169T>C polymorphism has also been identified as a risk factor of various autoimmune diseases, including rheumatoid arthritis, systemic lupus erythematosus, Hashimoto thyroiditis, Graves’ disease, and biliary cirrhosis." (PMID 23553198, 2013). "The FCRL3 immune response gene is mutated in autoimmune diseases such as rheumatoid arthritis, lupus, and Grave’s disease." (PMID 22929309, 2012). "Association of a functional promoter polymorphism mapping to the Fc receptor-like 3 (FCRL3) gene has recently been reported and replicated with rheumatoid arthritis (RA) in Japanese populations." (PMID 16859508, 2006). "In addition, a single nucleotide polymorphism in the FCRL3 promoter region binding of the NF-κB is associated with rheumatoid arthritis, autoimmune thyroid disease, and systemic lupus erythematosus." (PMID 37264476, 2023). "Therefore, the FCRL3 –169T>C polymorphism has previously been reported in association with rheumatoid arthritis, psoriasis vulgaris, neuromyelitis optica, multiple sclerosis and endometriosis." (PMID 30021560, 2018). "We further examined the relationship between SNP rs17676303 and other annotated SNPs in FCRL3 gene or its promoter region, namely rs7528684, rs3761969 and rs11264798, which have previously been identified as positively associated with GD, rheumatoid arthritis and systemic lupus erythematosus." (PMID 27863461, 2016). "The strongest evidence linking FCRL3 polymorphisms with autoimmunity is derived from linkage disequilibrium mapping of the chr1q21-23 region in rheumatoid arthritis, which identified 4 SNPs (rs7528684, rs11264799, rs945635 and rs3761959) in a Japanese population." (PMID 27863461, 2016). "Recently, polymorphisms of FCRL3 have been reported to be associated with rheumatoid arthritis (RA), systemic lupus erythematosus (SLE), Behcet’s disease, autoimmune thyroid disease (AITD), and multiple sclerosis (MS)." (PMID 19452015, 2009).
rheumatoid arthritis (continued). "The top 50 DEG include genes with variants previously associated with SS (CXCR5), SLE (CXCR5, PPP2CA, and TCF7), and rheumatoid arthritis (FCRL3)." (PMID 32650575, 2020). "The SNP rs7522061 in the FCRL3 gene was also reported to be associated with AITD in Caucasians and two other autoimmune diseases, rheumatoid arthritis (RA), and systemic lupus erythematosus (SLE)." (PMID 22242199, 2012). "However not all studies showed consistent association with polymorphisms in FCRL3, specifically no discernible association with FCRL3 were noted in some other rheumatoid arthritis populations including Caucasians in North American and European countries." (PMID 27863461, 2016). "Interestingly, rs7528684 has exhibited strong association with rheumatoid arthritis (RA) and anti-cyclic citrullinated peptide (CCP) antibody positivity in the Japanese population, hinting at FCRL3’s potential involvement in antibody production in autoimmune diseases." (PMID 40689332, 2025).
autoimmune disease (23 papers, 2008 to 2025). A disorder resulting from loss of function or tissue destruction of an organ or multiple organs, arising from humoral or cellular immune responses of the individual to their own tissue constituents. "Understanding the structure of FcRL3, particularly in the context of genetic variants, is therefore important for elucidating the pathogenesis of autoimmune diseases." (PMID 41300769, 2025). "Understanding the structure of FcRL3, particularly in the context of genetic variants, is also key to elucidating the pathogenesis of autoimmune diseases." (PMID 41300769, 2025). "FcRL3, encoded by a gene located on chromosome 1q21–23—a region associated with several autoimmune diseases—is of particular interest in the context of autoimmunity." (PMID 41300769, 2025). "We recently identified FCRL3, an orphan receptor expressed by lymphocytes and implicated in several autoimmune diseases, as a marker for the presence of the Sézary T cells in patients with high and medium tumor burden." (PMID 40723261, 2025). "Results of these surveys highlight the importance of FCRL3 polymorphisms in the pathogenesis of autoimmune diseases." (PMID 31341856, 2019). "Anti-apoA-1 IgG levels (a) independently predict all-cause mortality in the general population and (b) are linked to FCRL3, a susceptibility gene for numerous autoimmune diseases." (PMID 28458671, 2017). "Because of FCRL3’s association with these autoimmune diseases, the gene has now been considered as a candidate susceptibility gene for autoimmunity." (PMID 27446638, 2016). "The Fc receptor-like 3 (FCRL3) gene was reported to be linked to a variety of autoimmune diseases, including endometriosis-related infertility." (PMID 26334889, 2015). "The FCRL3 rs7528684 polymorphism has been shown to be a risk factor of various autoimmune diseases, including SLE, these results are inconsistent between distinct ethnicities." (PMID 25594855, 2015). "As a novel immunoregulatory gene, FCRL3 has been reported to be positively associated with various autoimmune diseases in different ethnic populations, though certain results were conflicting." (PMID 19452015, 2009). "Further studies of these SNPs and including other variants in the FCRL3 region, using larger (multi-center) patient numbers, and including various autoimmune diseases should be performed in the future." (PMID 19452015, 2009). "The polymorphisms of the Fc receptor-like 3 gene (FCRL3), −169C/T, −110A/G, +358C/G, and +1381A/G, have been reported to be associated with several autoimmune diseases." (PMID 19050767, 2008). "However, polymorphisms in the FCRL3 gene can induce Tregs dysfunction, leading to rapid autoreactive T-cell proliferation that causes autoimmune diseases." (PMID 41551875, 2025). "Genetic variants of FCRL3, especially the −169C/T polymorphism (rs7528684) within the promoter region, can influence protein expression and thus alter susceptibility to autoimmune diseases, including RA, systemic lupus erythematosus, and autoimmune thyroid disorders." (PMID 41300769, 2025). "Genetic variation in FCRL3 genes may affect the susceptibility to autoimmune diseases and exert their effects via different mechanisms." (PMID 31341856, 2019). "In this large population based study anti-apoA-1 IgG levels independently predicted all-cause mortality and were found to be linked to FCRL3, a susceptibility gene for numerous autoimmune diseases, which encodes a member of the immunoglobulin receptor superfamily." (PMID 29423541, 2018). "This suggests that FCRL3 polymorphisms may protect individuals from autoimmune diseases, which is somewhat consistent with our findings." (PMID 28702029, 2017). "It is necessary to clarify whether the discovered polymorphisms of FCRL3 are associated with other autoimmune diseases." (PMID 19050767, 2008).
autoimmune disease (continued). "In this study, we focused on the association of four FCRL3 SNPs with BD mainly because of the role this gene may play in the pathogenesis of autoimmunity and its association with other autoimmune diseases." (PMID 19050767, 2008). "The strong association of FCRL3 with autoimmune diseases further suggests that genetic polymorphisms within the extracellular domain may modify its ability to bind ligands or interact with other components of the immune system, thereby increasing disease susceptibility." (PMID 41300769, 2025). "In addition, four SNP candidates in FCRL3, including rs11264799, rs7528684, rs945635, and rs3761959, have been identified as potential risk factors in multiple autoimmune diseases, including RA, AITD, SLE, MS, autoimmune Addison’s disease, and autoimmune pancreatitis." (PMID 28702029, 2017). "This type of observation has also been described for the FCRL-3 gene, encoding a member of the Fc receptor-like family, specifically the C allele of FCRL3_3 variant has been associated with susceptibility to several autoimmune diseases but showed to be protective for MS, and Addison's disease." (PMID 19125193, 2009). "FCRL3 as a functional molecule within the immune system implies its potential role in autoimmune disease pathology, necessitating further investigation to elucidate genotype–phenotype correlations." (PMID 40689332, 2025). "Detailed knowledge of the molecular architecture of immune receptors such as FcRL3 is also essential for advancing our understanding of immune function and for guiding the development of targeted therapeutic strategies in autoimmune disease." (PMID 41300769, 2025). "FCRL3 is a receptor expressed on lymphocytes and has been found to be connected to various autoimmune diseases." (PMID 40468464, 2025). "Given the documented role of FcRL3 in regulating immune responses and its involvement in the pathogenesis of autoimmune diseases such as RA, this receptor represents an attractive target for new therapeutic strategies." (PMID 41300769, 2025). "A detailed knowledge of the molecular architecture of immune receptors such as FcRL3 is crucial both for advancing our understanding of immune system function and for guiding the development of targeted therapeutic strategies for autoimmune disease." (PMID 41300769, 2025). "Elevated FcRL3 expression has also been observed in inflamed tissues of patients with autoimmune diseases, including RA and systemic lupus erythematosus, supporting its direct involvement in disease pathogenesis." (PMID 41300769, 2025). "FCRL3 (Fc receptor-like 3 gene), a novel immunoregulatory gene, has recently been reported to play a role in autoimmune diseases." (PMID 25594855, 2015). "The polymorphisms of the Fc receptor-like 3 gene (FCRL3), a novel immunoregulatory gene, have been shown to be associated with certain autoimmune diseases." (PMID 19452015, 2009). "Thus, elevated FCRL3 expression disturbs the immune-suppressive roles of Tregs via the cytoplasmic motif (ITIM) and causes autoimmune diseases, including RA." (PMID 41551875, 2025). "FCRL3 was documented to be involved in many autoimmune diseases." (PMID 36387234, 2022). "Until now, there are no consensus results on the association of FCRL3 polymorphism and susceptibility to autoimmune disorders." (PMID 31341856, 2019). "The FCRL3 protein has been found to be prevalent in autoimmune disorders." (PMID 27446638, 2016). "Variants in the FCRL3 gene have been previously associated with autoimmune diseases, but such associations have not been reported for ABO blood group genotypes." (PMID 21829393, 2011). "Located in the lq21 region, FCRL3 encodes a Fc receptor-like (FCRL) molecule exhibiting significant structural homology with Fc region immunoglobulin receptors, implicating its role in various autoimmune diseases such as psoriasis, Sjogren’s syndrome, and autoimmune thyroid disorders." (PMID 40689332, 2025).
autoimmune disease (continued). "Therefore, these two polymorphism loci would not be chosen as target SNPs of FCRL3 gene to investigate the genetic pathogenic process of the autoimmunity diseases, or AR." (PMID 25594855, 2015). "The polymorphisms of FCRL3 were reported to be associated with RA in Japan and MS in Spain, but the associations could not be replicated completely in other autoimmune diseases." (PMID 19452015, 2009).
Graves disease (15 papers, 2006 to 2024). Graves' disease is an autoimmune disorder that leads to overactivity of the thyroid gland (hyperthyroidism).It is caused by an abnormal immune system response that causes the thyroid gland to produce too much thyroid hormones. "Pooled genome wide association study identified a genetic variant upstream of FCRL3 as a susceptibility locus for Graves’ disease in addition to those identified in the Major Histo-compatibility Complex." (PMID 27863461, 2016). "Rs17676303 on chromosome 1q23.1, located upstream of FCRL3, showed evidence of association with Graves’ disease across the discovery, replication and combined cohorts." (PMID 27863461, 2016). "In support of this, a study in the UK population has replicated association of the FCRL3-169*C/T gene polymorphism with Graves' disease but with a smaller effect size." (PMID 16859508, 2006). "The aberrant expression of FCRL3 in autoimmune thyroid diseases, Grave’s disease, systemic lupus erythematosus (LES), and pSS has already been noted, while its exact function in pSS is not clear yet." (PMID 37176092, 2023). "Among these, PTPN22, CTLA4, HLA_DRB1, FCRL3, and IL2RA are common susceptibility genes between both conditions, while CD40 is exclusively associated with Graves’ disease and RA." (PMID 38093966, 2023). "rs11264798 located in intron 8 of FCRL3, and rs10489678 in FCRL5, have been previously associated with Graves' disease." (PMID 21829393, 2011). "The 1q23/FCRL3 association data highlight the complexity of this autoimmune locus, which has previously been associated with SLE, RA and Graves' disease." (PMID 21829393, 2011).
systemic lupus erythematosus (14 papers, 2008 to 2025). An autoimmune multi-organ disease typically associated with vasculopathy and autoantibody production. "However, we did not study other known markers for Tregs such as CD127 and Helios which have already been evaluated in lupus or new markers such as TIGIT or FCRL3." (PMID 26629828, 2015).